CD24 (CD24 molecule)
Diseases named in the same sentence as CD24 in open-access papers (continued):
Sharing a sentence is not in itself a finding about the gene and the disease.
cancer (continued). "Further, in accordance with the increased expression of pluripotency and stemness-related genes, flow cytometric analysis of ALDH activity and CD44/CD24 expression corroborated the presumptive induction of an enhanced cancer stem cell phenotype upon overexpression of β-catenin in TNBC cells." (PMID 34367990, 2021). "Here, we propose a novel targeted cancer therapeutic platform based on the lentiviral integrase, stimulated by integrase-derived peptides, that are specifically delivered to cancerous cells via CD24 antigen-antibody targeting." (PMID 33958722, 2021). "Second, we did not assess other risk factors that may be associated with elevated risk of blood cancers, which could confound or mediate the relationship between CD24 and prevalence of cancer." (PMID 34442367, 2021). "Interestingly, the CD44/CD24 ratio, which positively correlates with the malignance of cancer, was the highest in H1975." (PMID 34127680, 2021). "Therefore, CD24 has attracted much attention as a potential molecule to target cancer cells/cancer stem cells." (PMID 34363319, 2021). "The new recent concepts on CD24 open interesting perspectives for innovative cancer treatments." (PMID 33806857, 2021). "The majority of prostate cells in BPH non-cancer specimens were CD44-/CD24+ and CD44-/CD24-." (PMID 34019593, 2021). "However, full evaluation of the therapeutic efficacy of mAb-mediated blockade of CD24:Siglec-10 interactions in cancer patients warrants further investigation." (PMID 34638388, 2021). "CD24 expression has been evaluated as a prognostic marker of poor survival in many types of cancer." (PMID 34575716, 2021). "In conclusion, our findings may assist in further development and optimization of the CD24/CD11b biomarker to serve as a cancer screening test for early detection of cancer among the healthy population." (PMID 34575716, 2021). "It is still unknown whether CD24 blockade in vivo can effectively bridge innate immunity and adaptive immunity, thereby enhancing the immune clearance of cancer cells." (PMID 34363319, 2021). "CD44+ CD24+ CD133+ cells exhibited biological properties of cancer stem-like cells." (PMID 34094034, 2021). "A recent review has shed light on the use of CD24 as a target for cancer therapy." (PMID 33499388, 2021). "Our data demonstrate that anti-CD24-based cancer immunotherapy has potential clinical application and might be applicable to hematological malignancies." (PMID 34442367, 2021). "The subcellular localization of CD24 was studied in a variety of cancer types and one could be at liberty to argue that, overall, CD24 was found to reside at the plasma membrane, the cytoplasm, and the nucleus." (PMID 34360932, 2021). "There is extensive research on the correlation between CD24 and cancer." (PMID 34575716, 2021). "In addition, CD24 has been proposed as a biomarker for the active proliferation of several types of cancer stem cells." (PMID 34363319, 2021). "In addition to its importance as a prognostic biomarker, CD24 is considered a target for anti-cancer therapies." (PMID 33806857, 2021). "Based on these findings, CD24 is being investigated as a marker for early detection of cancer." (PMID 34575716, 2021). "Moreover, sialylLewisx (sialylLex), a SA-bearing glycan, controls CD24 facilitated rolling of cancer cells on P-selectin and extravasation during metastasis." (PMID 33889547, 2021). "It is interesting to note that the CD24–Siglec-10 binding axis has adverse effects in human cancer." (PMID 34360811, 2021). "In SPNs-treated PANC-1 cells, under-expression of miR-155, miR-21, and miR-222 in association with the decrease in CD markers CD24, CD44, and CD133 may indicate the importance of SPNs in inhibition of onco-miRs and stemness properties of PANC-1 cancer cells." (PMID 34094034, 2021).
cancer (continued). "Moreover, expression of the cancer stem cell surface marker CD44+CD24-/low subpopulation, which is measured by flow cytometry and mammosphere forming efficiency, was also reduced after NUP37 downregulated." (PMID 34386417, 2021). "Targeting CD24 in directed drug development showed promising results in cancer treatment." (PMID 33915986, 2021). "Besides, cancer cells expressing CD24 can escape detection by the immune system by interacting with the inhibitory receptor SA-binding Ig-like lectin 10 (Siglec-10)." (PMID 33889547, 2021). "In particular, CD24 is overexpressed in many cancers and appears to be oncogenic." (PMID 33800141, 2021). "Thus, blockage of the CD24 effect by its monoclonal antibodies effectively enhances the ability of TA‐MACs to attack various types of cancer cells." (PMID 34363319, 2021). "At the same time, CD24, the P-selectin ligand, has been found in several human carcinomas." (PMID 34439397, 2021). "For the specific characterization by flow cytometry and confocal microscopy, different commercial antibodies against selected receptors were used, including the general tetraspanins CD9, CD63 and CD81, and cancer-related receptors (CD24, CD44, CD54, CD326 and CD340)." (PMID 32054015, 2020). "Interestingly, the immunomagnetic separation of the exosomes based on CD81 is not affected by the serum (even if it is undiluted), which can be easily detected by an electrochemical immunosensor using cancer related biomarkers, such as CD24 and CD340." (PMID 32054015, 2020). "The cancer stem cell markers, CD24 and CD44, were also monitored." (PMID 33233485, 2020). "In addition, a recent study revealed that CD24, a new “Don’t eat me” signal, interacted with Sialic acid Ig like lectin 10 (Siglec-10) to prevent macrophages from clearing cancer cells." (PMID 33597922, 2020). "Studies have suggested that CD24 regulates different signaling pathways in various cancer cells." (PMID 32394616, 2020). "The significantly increased gene expression of CD24, as an important marker of cancer stem cells (CSCs), was detected in PC-9-Br compared to PC-9 parental, which may be another metastatic mechanism in this LCMB model." (PMID 32264860, 2020). "In contrast, CD24 has been systematically investigated in various cancers." (PMID 32716908, 2020). "It seems promising that the therapeutic potential of CD24 blockade with monoclonal antibodies, which may promote the phagocytic clearance of CD24+ cancer cells both in vitro and in vivo." (PMID 33424840, 2020). "The CD44+/CD24- subpopulation of cancer cells was determined under 6-methoxymellein." (PMID 32977636, 2020). "CD24 protected cancer cells escaped engulfing by macrophages." (PMID 33324558, 2020). "These cells,named tumor initiating cells or cancer stem cells (CSCs),could generally be identified based on the expression of avariety of cell surface markers such as CD24, CD44, CD133,CD166, Trop-1 and EpCAM." (PMID 30825285, 2019). "Our group has recently experienced the ability of DCA to reduce the expression of cancer stem cell markers CD24/CD44/EPCAM in a pancreatic cancer cell line as well as to compromise spheroid formation and viability, further corroborating data obtained in other cancer models." (PMID 31827705, 2019). "Notably, DCA downregulated the expression of the cancer stem cells markers CD24/CD44/EPCAM only in PANC-1 but inhibited spheroid formation/viability in both cell lines." (PMID 31109089, 2019). "CD24 has also been reported to promote cancer cell angiogenesis." (PMID 31624236, 2019). "CD44+/CD24- cancer cells were assessed under sulconazole treatment." (PMID 31480284, 2019). "Interestingly, siBRCA1 treatment resulted in significant increase in the expression of cancer stem cell-associated markers including CD44, ALDH1A3, and OCT4, while leading to down-regulation of CD24 (p < 0.0001 for all pair-wise comparisons)." (PMID 31273285, 2019).
cancer (continued). "Furthermore, we observed that Skp2 downregulation led to the decrease in subpopulation of CD44+CD24− cancer stem-like cells." (PMID 30952903, 2019). "CD24+ cell accumulation on the solid tumors’ sides was observed, which may provide valuable insight for designing new drugs to target cancer subpopulations with high metastatic potential." (PMID 30728024, 2019). "We observed that mesenchymal cells are enriched in a CD44+CD24− cancer stem cell subpopulation." (PMID 30952903, 2019). "Overexpression of CD24 has been reported in many cancer studies." (PMID 31624236, 2019). "Furthermore, identification of protein markers such as ALDH1A1, Sox2, CD44, Oct4, CD133, CD24, and Nanog, etc. have been vital in studying CSCs in cancer research." (PMID 31530793, 2019). "Moreover EVs are becoming increasingly important in monitoring cancer progression and therapy, since they are able to carry specific disease biomarkers such as Glypican-1, colon cancer-associated transcript 2, CD63, CD24, and many others." (PMID 31281356, 2019). "The knockdown of CD24 attenuated cancer stemness properties." (PMID 30327565, 2018). "The results of this research indicated that the introduced Nano contrast could be helpful for detection of the cancer cells, which highly express CD24 antibody based on clinical application of CT scans." (PMID 30607332, 2018). "Specifically, the CD44+/high, CD24+/low cancer cellsbelong to the low grade, luminal subtype." (PMID 29845782, 2018). "CD24 has also been largely studied as a cancer stem cell marker in many different types of cancers." (PMID 30551640, 2018). "Previous studies have focused on the engagement of CD24 early in B cell development and when expressed in transformed cancer cells, where it plays an important role as an adhesion molecule regulating survival and allowing spread throughout tissues and lymphatics respectively." (PMID 30405620, 2018). "Using the same cut-off as of training cohort, the individual sensitivity and specificity for cancer detection were 35.0% (21/60) and 91.3% (167/183) for CD24, 35.0% (21/60) and 83.6% (153/183) for CD49f, and 51.7% (31/60) and 88.5% (162/183) for NANOG, respectively." (PMID 30327565, 2018). "Given that CD24 is a proven marker for cancer stem cells in ovarian cell populations, CD24 could provide a novel target for therapy." (PMID 29047224, 2017). "To clarify whether polyploid cells or their progeny exhibit cancer stem cell-like properties, we analyzed the numbers of CD24, CD44 and CD133 positive cells, using H33342 staining as a ploidy discriminator." (PMID 28030837, 2017). "It was observed that ACEA decreased CD44+/CD24-/low/ESA+ cancer stem cell invasiveness." (PMID 29552056, 2017). "In addition, after the induction of differentiation, cancer cells reached levels of CD24 similar to those observed in the parental cells." (PMID 28611669, 2017). "Therefore, CD24 promotes cancer cell migration and metastasis by facilitating the attachment of cancer cells to activated platelets and endothelial cells." (PMID 28445439, 2017). "The discovery of CD44+/CD24- cells has generated excitement and led to efforts in multiple laboratories to find vulnerability for this subpopulation, as this subpopulation of cancer cells may represent a therapeutic target to anticancer drugs." (PMID 29190901, 2017). "Interestingly, changes in the patterns of expression of these other cancer stem cell markers were different from those of CD24 expression." (PMID 28418843, 2017). "CD24, the cell surface protein, is highly expressed in many human cancers." (PMID 27304054, 2016). "In line with this hypothesis, cancer cells expressing SOX2 showed an increased expression of the stem cell markers CD24 and CD44." (PMID 27411517, 2016).
cancer (continued). "Using the tumorsphere assay we demonstrated that CD24+ Mvt-1 cells possess cancer stem-like cells characteristics, and we tested whether this phenotype is IGF1R-dependent." (PMID 27179633, 2016). "Furthermore, CD24 expression has been shown to have prognostic relevance for the survival of patients suffering from a variety of cancer types, including breast and prostate." (PMID 26978528, 2016). "Several steps towards marketing a CD24 mAb as a cancer therapeutic have been made." (PMID 26891329, 2016). "To further investigate whether overexpression of CD44 and CD24 plays roles in reprogramming differentiated cancer cells to CSC-like phenotype, we ectopically expressed CD44 and CD24 in NPC parental cells." (PMID 27521216, 2016). "In this study, we suggest that CD24 cell surface expression in cancer cells may predict sensitivity to anti-IGF1R therapy." (PMID 27179633, 2016). "CD24 mediates cell-cell interactions as a surface marker that is expressed on cancer cells." (PMID 26506239, 2016). "Unlocking the CD24 signaling mechanism may have wide-ranging implications in understanding the regulation of cell fate determination in normal and cancer cells." (PMID 28083532, 2016). "Using RNA-seq analysis, we have identified SLPI among the top three upregulated genes in the highly tumorigenic CD24+ Mvt1 cell subset, and suggests that SLPI may play a role in the more aggressive cancers derived from CD24+ cells." (PMID 27179633, 2016). "CD24 is a small, heavily glycosylated, GPI-linked membrane protein, whose expression has been associated with the tumorigenesis and progression of several types of cancer." (PMID 26978528, 2016). "Thus while CD24 positivity can define populations enriched for CSCs in human carcinomas of the pancreas and ovary, CD24 negativity enriches for putative human breast and prostate CSCs." (PMID 26978528, 2016). "Second, do CD24+ cells act as stem/progenitor cells and are CD24− cancer cells their progeny?" (PMID 26040280, 2015). "Its overexpression during cancer progression and its prognostic significance have been reported for many types of cancer including breast, colorectal, gastric, lung, ovarian, pancreatic, and prostate cancers, supporting the usefulness of CD24 as a cancer marker for diagnosis and prognosis." (PMID 26444008, 2015). "However, when stratified according to histology, AC displaying the putative cancer stem cell (CSC) signature CD24−/CD44+ had a significantly shorter overall survival than CD24+/CD44− AC." (PMID 26578846, 2015). "After 20 days, tumors were harvested and cancer cells were analyzed by FACS for CD24 expression." (PMID 26040280, 2015). "Similarly to EVs from serum, exosomes from BrCa pleural effusions contained ADAM10, CD9, and CD24 but also contained the epithelial cell adhesion molecule (EpCAM), a highly expressed protein on cancer cells." (PMID 26601108, 2015). "Moreover, ectopic expression of Snail or Twist or exposure to TGF-β induces EMT in immortalized human mammary epithelial cells (HMLE) and increases the formation of tumor spheres and CD44+/ CD24− cells, also known as cancer stem-like cells (CSCs)." (PMID 26462028, 2015). "CD24 is a cell surface protein that has various and diverse roles in cell adhesion and signaling, B lymphocyte and neuronal development, autoimmune diseases, and cancer." (PMID 26301220, 2015). "Furthermore, OPG upregulated the expression of the cancer initiating cell marker CD24, in HMEC spheres." (PMID 26608463, 2015). "The 4-hour time point also appears to be the optimum duration for the separation and enrichment of the breast CSCs (as denoted by the phenotype of CD44+CD24−/lowESA+) from the heterogeneous MCF7 cancer cells and the primary cells under static culture conditions." (PMID 25905435, 2015). "Further studies should clarify, if an adjuvant therapeutic use of CD24 antibodies may have an additive value in cancer treatment." (PMID 26578846, 2015).
cancer (continued). "Importantly, CD24 was recently identified as a cancer stem cell marker in various types of cancer including pancreatic and lung cancers." (PMID 26444008, 2015). "Expression of CD24 might facilitate the interactions of cancer cells with endothelial cells and platelets, which promotes the dissemination of CD24-expressing cancer cells." (PMID 25503963, 2014). "The cell surface protein, CD24, is highly expressed in many human cancers." (PMID 24955581, 2014). "CD24 expressed on cancer cells interacts with P-selectin found on endothelial cells, indicating that CD24 may bind to P-selectin and initiate rolling of cancer cells on the endothelium, which may be followed by initiation of metastasis." (PMID 24955581, 2014). "CD24 is an adhesion mucin-like molecule, and its expression could increase the ability of cancer cells to metastasize and invade lymph nodes." (PMID 24708742, 2014). "Significantly, the CD44+/CD24−/Low subpopulation revealed higher centrosome amplification compared to bulk SUM149PT cancer cells, suggesting that the higher degree of CIN observed in SUM149PT cancer cells was functionally linked to the genesis of CD44+/CD24−/Low CSCs harboring amplified centrosomes." (PMID 24970653, 2014). "Up-regulation of CD24 could increase actin cytoskeletal remolding dynamic and enhance contractile forces to facilitate cancer cell invasion." (PMID 24010737, 2013). "However, the increased expression of CD24 surface marker exacerbated the cancer stem cell properties of treated U87-MCSF cells." (PMID 24391839, 2013). "The CD44/CD24 immunophenotypes behavior shows great diversity in human cancers." (PMID 23419168, 2013). "CD24 has also been reported to be a ligand for P-selectin, an adhesion receptor on activated endothelial cells and platelets, suggesting that the molecule functionally enhances the metastatic potential of cancer cells." (PMID 23946784, 2013). "This correlation suggests that CD24 plays an important role in metastatic events in human cancers." (PMID 23419168, 2013). "Moreover, these CD24−/low cells were much more tumorigenic than controls suggesting that the CD8+ T cell-dependent immune response was inducing EMT in the cancer cells to generate CSCs." (PMID 23986719, 2013). "3±8), with 15/139 (20.2%) cases being positive, that is, expressing CD24 in ⩾10% of cancer cells." (PMID 22333601, 2012). "However, CD44 is expressed in almost all cancers, likewise, recent reports show CD24 is also enriched in ovarian CSCs." (PMID 22693526, 2012). "CD24 is rarely expressed on normal cells, but may be highly expressed on stem cells of cancers including pancreatic, ovarian and colorectal ones." (PMID 23166783, 2012). "This indicates the distinct expression and function of CD24 in different cancers." (PMID 22693526, 2012). "To examine whether CD44+CD24-ESA+ or CD44+CD24+ESA+ cells are cancer stem-like cells and to further investigated their tumorigenic potential, we implanted 10,000, 1,000, and 100 cells into the mammary fat pads of nude mice." (PMID 22901246, 2012). "However, CD24 has been identified as a novel regulator of proliferation, apoptosis and invasion in human cancer." (PMID 22731636, 2012). "Also, in our preliminary study on selected cancer cell lines, we observed a range of variation in CD44 and CD24 expression even amongst same cancer types." (PMID 22693526, 2012). "In addition to being enriched in prospective stem cell signatures, OTBCs were enriched in the tumorigenic, cancer stem cell CD44+/CD24- signature." (PMID 21952072, 2011). "Furthermore, over-expression of both HMGA2 forms was associated with a strong repression of the epithelial marker CD24, consistent with the reported low level of CD24 in cancer stem cells." (PMID 20576167, 2010). "In addition, disseminated cancer cells in bone marrow with CD44+/CD24- phenotype have been identified in patients, although the prognostic relevance of this is as yet unclear." (PMID 20691079, 2010).